GSDMB (gasdermin B)
Diseases named in the same sentence as GSDMB in open-access papers (continued):
Sharing a sentence is not in itself a finding about the gene and the disease.
asthma (continued). "So far, GSDMB has been reported in several diseases, most documented in asthma, cancers, and inflammatory bowel diseases." (PMID 38693919, 2024). "Mutations in these genes, including ORMDL3, GSDMB, ZPBP2, and IKZF3, result in reduced protein folding in the endoplasmic reticulum leading to an overall pro-inflammatory effect in asthma patients." (PMID 39237910, 2024). "The suspected role of GSDMB in asthma is based on apoptosis of epithelial cells regulation, hence cell proliferation, differentiation, moreover upregulation of the expression of airway remodeling genes, chemokines, and heat-shock proteins." (PMID 38693919, 2024). "While the genetic analyses have identified the association between GSDMB and interferon response, the molecular mechanisms and ensuing biological effects of GSDMB in mtDNA-induced cGAS-STING pathway in the context of asthma remain largely undefined." (PMID 38737375, 2024). "The reason for this review is to provide a definition and clarification on the GSDMB gene, and how it relates to immunological and inflammatory processes and to consider the reasons for different impacts it has on adult and pediatric asthma." (PMID 40104184, 2024). "Among the protein-coding genes causally associated with unspecified asthma in lung and blood, seven are within the 17q12-21 locus (i.e., PGAP3, IKZF3, GSDMB, ORMDL3, GSDMA, MED24, and CASC3)." (PMID 39628479, 2024). "GSDMB/ORMDL3 has previously been associated with ICS response and exacerbations for common variants, asthma for common variants, and asthma for the combined effect of rare and common variants." (PMID 38674355, 2024). "Gasdermin B (GSDMB) is highly expressed in the epithelium in asthma, and increased GSDMB expression in transgenic mice leads to spontaneous remodelling and AHR in the absence of airway inflammation." (PMID 38609094, 2024). "The gene cluster comprising ORMDL3 and gasdermin B (GSDMB) is located on chromosome 17q21 and is strongly associated with asthma." (PMID 38562155, 2024). "GSDMB is involved in some immune diseases, such as asthma and inflammatory bowel disease, and is also expressed in immune cells." (PMID 38711020, 2024). "Previous research has established a strong correlation between GSDMs and sterile inflammation, as indicated by the association of Gsdma3 with alopecia induced by skin inflammation and that of GSDMB with childhood asthma 7-10." (PMID 37781519, 2023). "Previously, GSDMB-related research has been more active in asthma, while our study fully characterizes GSDMB in patients with LUAD." (PMID 37705753, 2023). "In the STEPS study, asthma risk alleles in IKZF3, GSDMA, GSDMB, ZPBP2, and ORMDL3 genes were associated with a higher risk of a wheezing illness (all P values ≤.02)." (PMID 36967681, 2023). "In asthma, higher GSDMB expression is correlated with increased interferon signaling and MHC class I antigen presentation." (PMID 37120605, 2023). "Isoform 1 of GSDMB is overexpressed in bronchial epithelial cells of asthma patients and is located in the nucleus." (PMID 37771587, 2023). "Asthma risk alleles in GSDMA, GSDMB, IKZF3, ZPBP2, and ORMDL3 genes were associated with wheezing illnesses in early childhood, especially rhinovirus-positive wheezing illnesses." (PMID 36967681, 2023). "The rs8067378 and rs2305480 in GSDMB were found to be protective SNPs for cervical squamous intraepithelial lesion and asthma, respectively; while GSDMB-rs2290400 was correlated with asthma combined with allergic rhinitis." (PMID 37359371, 2023). "The asthma L-GRN includes HLA genes and other genes previously reported to be associated with asthma (e.g., PRKCQ, GSDMA, and GSDMB)." (PMID 37680636, 2023). "SNPs of GSDMB are associated with several chronic inflammatory diseases, such as IBD, rheumatoid arthritis, and asthma." (PMID 37771587, 2023).
asthma (continued). "Most markedly, the “17Q12-21” locus, which has been simulated in numerous GWASs and harbors numeral probable biologic candidate genes, comprising ORMDL3 and GSDMB, has been concerned in the development of asthma." (PMID 36225476, 2022). "The human GSDMA and GSDMB genes are located on chromosome 17 (17q12-21) together with other prime candidates asthma genes such as ORM1-like gene (ORMDL3) and post-GPI attachment to proteins 3 (PGAP3)." (PMID 36201519, 2022). "In other animal studies, an overexpression of asthma genes located in chromosome 17q21 (including gasdermin B (GSDMB) and human orosomucoid-like 3 (ORMDL3)) have been detected." (PMID 35629272, 2022). "GSDMB polymorphisms and/or expression levels have been associated with allergic and inflammatory diseases, such as asthma and inflammatory bowel disease (IBD), with some disease-associated GSDMB variants linked to decreased activity." (PMID 35608339, 2022). "They identified the asthma gene GSDMB and showed that by studying interconnecting genes it is possible to identify potential mediators of the interactions between different phenotypes." (PMID 35331221, 2022). "Expression and function of gasdermin B, encoded by GSDMB, has been directly linked to genetic variation at the core region of the 17q12-q21 locus and to processes relevant to asthma." (PMID 36175932, 2022). "Collectively, these data support our suggestion about the significant correlation between GSDMB and IgE serum level in asthmatics, but in a way independent on asthma status, in addition to the involvement of other factors that interfere with this association." (PMID 36201519, 2022). "Some genes were linked to specific asthma phenotypes, including ORMDL3/GSDMB/LRRC3C (17q21.1), which is linked with childhood asthma." (PMID 36294997, 2022). "The minor allele A of rs2872507 in GSDMB was the risk allele for RA and IBD (Crohn’s disease and ulcerative colitis) but was a protective allele for asthma." (PMID 35720396, 2022). "Genome-wide association studies (GWAS) implicated that the polymorphisms in GSDMB were markedly associated with IBD, asthma, and type I diabetes." (PMID 35720396, 2022). "The locus 17q12-21 encodes several genes including ORMDL3, GSDMB, ZBPB2, and IKZF2, which in fact were linked to asthma in subsequent GWAS and eQTL analyses, and it is one of the most replicated asthma loci to date." (PMID 35055381, 2022). "For wheeze at month 18, we found significant associations of UMC only in the asthma risk strata of the single-nucleotide polymorphisms at the 17q21 locus related to ORMDL3 (rs8076131) and GSDMB (rs7216389 and rs2290400, all p-values for interaction < 0.001)." (PMID 33986744, 2021). "Variants of the complex 17q21 region affecting GSDMB and ORMDL3 were previously found to be determinant for childhood asthma susceptibility and development of Rhinovirus-induced wheezing in preschool age." (PMID 33925009, 2021). "A study of Korean children revealed that the susceptibility to asthma and intermediate asthma phenotypes, such as elevated IgE and bronchial hyperresponsiveness, is associated with GG of GSDMA (rs7212938) and TT of GSDMB (rs7216389)." (PMID 34858408, 2021). "The exceptions were four variants located on chromosomes 1q21.3 (in/near TCHHL1, HRNR, FLG and SPRR2A) which had significantly stronger effects on age-of-onset of eczema, and one on 17q12 (in GSDMB) which had a stronger effect on the age-of-onset of asthma." (PMID 32603359, 2020). "GSDMB is highly expressed in bronchial epithelial cells from subjects with asthma and expression is correlated with disease severity." (PMID 32887352, 2020). "Chromosome 17q21 is an area of interest for asthma and contains a cluster of genes linked to asthma in several GWAS studies, including the GSDMB (Gasdermin B) and IKZF3 (Ikaros family zinc finger protein 3) genes." (PMID 33133517, 2020). "The chromosome 17q21 locus that carries GSDMB and ORMDL3 harbors more than a dozen SNPs linked to asthma." (PMID 32500120, 2020).
asthma (continued). "One of the most well replicated genetic regions affecting asthma risk is the 17q12–21 locus, which includes ORMDL3 and GSDMB." (PMID 31443563, 2019). "The already presented SNP rs12936231 has been reported as a high-risk allele for asthma and autoimmune diseases and suggested to cause chromatin remodeling and alter transcription of certain genes, including ZPBP2, GSDMB, and ORMDL3." (PMID 31362752, 2019). "In fact, early studies had revealed that SNPs associated with asthma co-regulate the expression of ORMDL3, GSDMB, and ZPBP2 in Latinos." (PMID 30805318, 2019). "We also identified independent missense associations for genes and phenotypes such as ENPEP and hypertension; GSDMB and asthma; IFIH1 and hypothyroidism; and PALB2 and lung cancer." (PMID 29691392, 2018). "We showed associations with known asthma loci in IL1RL1, IL13, LINC01149, near GSDMB, and in the C11orf30-LRRC32 region." (PMID 30373671, 2018). "The first childhood asthma GWAS identified common regulatory variants at and near the ORMDL3/GSDMB/ZPBP2 loci on chromosome 17q21 in three populations of European ancestry, a finding that has now been confirmed in various ethnic groups." (PMID 30086710, 2018). "A number of prior GWAS have identified distinct genetic susceptibility for pediatric onset asthma, particularly implicating ORLDM3/GSDMB, IL1RL1, and IL13, which were all found to have association with childhood asthma in the current analysis." (PMID 30373671, 2018). "One exome study found some evidence of population-specific low-frequency variants being associated with asthma in the following genes: GRASP and GSDMB among Latinos, and MTHFR among African Americans/African Caribbeans." (PMID 28774304, 2017). "Specific to asthma, differential expression at the ZPBP2/GSDMB/ORMDL3 locus was identified resulting from allele-specific chromatin remodeling mediated by CTCF." (PMID 29228930, 2017). "The most well-known and highly replicated asthma association signal is within the 17q21 locus that includes the ORMDL3 and GSDMB genes." (PMID 28774304, 2017). "Among asthma susceptibility genes, ORMDL3 and GSDMB, with SNP rs2305480 at chromosome 17q21, are associated with childhood asthma." (PMID 27658857, 2016). "Polymorphisms in ADAM33 (rs511898 and rs528557) and ORMDL3/GSDMB (rs7216389) were negatively associated and polymorphisms in IL4 (rs2070874 and rs2243250) were positively associated with childhood asthma." (PMID 25768087, 2015). "Although the region covering the ORMDL3, GSDMA and GSDMB genes is the most replicated one, the keratin (KRT) cluster has also been shown to be associated with asthma in a previous GWAS study." (PMID 26672748, 2015). "Polymorphisms in ADAM33, ORMDL3/GSDMB and IL4 were associated with childhood asthma in a group of children with recurrent wheeze." (PMID 25768087, 2015). "It remains to be seen also if GSDMB splicing changes are also noted in individuals with asthma and autoimmune diseases." (PMID 24044605, 2013). "GSDMB SNP rs2305480 (Ser311Pro) was associated with asthma diagnosis (p = 8.9×10-4), BHR (p = 8.2×10-4) and severity (p = 1.5×10-4) with supporting evidence from a second GSDMB SNP rs11078927 (intronic)." (PMID 24066901, 2013). "The extended chromosome 17 locus has also been implicated previously as containing SNPs associated with asthma spanning three main genes; ZPBP2/GSDMB/ORMDL3 and it is still unclear which genes/polymorphisms underlie these associations." (PMID 24066901, 2013). "A very recent GWA study of severe asthma in Europeans found strong evidence for two previously established loci (ORMDL3/GSDMB and IL1RL1/IL18R1) in patients with severe asthma but did not identify any novel loci." (PMID 23028483, 2012). "They observed associations with asthma, particularly childhood-onset asthma, at multiple loci (ORMDL3/GSDMB, IL1RL1/IL18R1, HLA-DQ, IL33, SMAD3, and IL2RB)." (PMID 23028483, 2012).
asthma (continued). "Targeting GSDMB could enhance its tumor-suppressive effects in cancer while alleviating chronic inflammation in diseases like asthma and IBD." (PMID 40452932, 2025). "Higher GSDMB levels are also associated with reduced type 2 immunity in nasal brushings from children, regardless of their asthma status." (PMID 40687950, 2025). "This may explain why rs7216389, rather than rs4065275, was associated with exacerbations in this study, suggesting a greater involvement of GSDMB than ORMDL3 in exacerbations in type 2–low asthma." (PMID 40687950, 2025). "It remains uncertain whether GSDMB or ORMDL3 plays a critical role in exacerbations in patients with type 2–low asthma, although the role of GSDMB has received more attention recently." (PMID 40687950, 2025). "Other genes within this locus, including ORMDL3 and GSDMB, have studies not only demonstrating their genetic epidemiologic linkage to asthma, but also studies of their biology implicating them in the pathogenesis of asthma and airway remodeling." (PMID 40131902, 2025). "The GSDMB gene is involved in the regulation of immune responses, particularly in the activation of inflammasomes, which play a crucial role in airway inflammation seen in asthma." (PMID 39906448, 2025). "Recent genetic studies have identified Gasdermin B (GSDMB) polymorphisms as contributors to enhanced Type-2 cytokine responses in asthma, underscoring potential upstream regulatory mechanisms influencing Th2 biomarkers expression and asthma remission." (PMID 40503233, 2025). "Another disorder in which GSDMB has been investigated is asthma." (PMID 38693919, 2024). "Like GSDMB, increased expression of ORMDL3 has been linked to interferon signaling and immune response in the context of asthma, and we suggest that similar regulatory pathways may play a role in susceptibility to severe bronchiolitis." (PMID 39299705, 2024). "Furthermore, GSDMB SNPs and expression in AECs correlate to human asthma severity and exacerbations." (PMID 39611173, 2024). "Notably, GSDMB is upregulated in the bronchial epithelium of asthma patients, and its overexpression in mice induces airway hyperresponsiveness and remodeling." (PMID 39611173, 2024). "Higher expression of GSDMB is correlated with antiviral pathways and exacerbations of asthma." (PMID 38225586, 2024). "Hence, our findings provide novel molecular insights into how the genetic determinant GSDMB regulates lung inflammation in asthma development, suggesting a promising therapeutic strategy for treating airway inflammation in genetically susceptible asthmatics." (PMID 38737375, 2024). "Additionally, it has been demonstrated in the past that mice that express higher amounts of human GSDMB or human ORMDL3 have an asthma phenotype 17." (PMID 40104184, 2024). "The asthma risk alleles in CDHR3, GSDMA, and GSDMB were associated with an increased rate of ARIs (for CDHR3, incidence rate ratio [IRR], 1.06; 95% confidence interval [CI], 1.01–1.12; P = .02), and risk allele in CDHR3 gene with rhinovirus infections (IRR, 1.10; 95% CI, 1.01–1.20, P = .03)." (PMID 36967681, 2023). "In fact, GSDMB is highly expressed in the airway epithelial cells of asthmatic individuals, indicating that activated GSDMB may induce caspase-mediated pyroptosis in these cells and trigger asthma." (PMID 37250902, 2023). "The expression of GSDMB in airway epithelial cells of patients with asthma is upregulated." (PMID 35967302, 2022). "In our earlier study, we showed that expression of GSDMB in airway epithelial cells, but not in peripheral blood cells, modulated the risk for childhood-onset asthma at the 17q12-q21 locus." (PMID 36175932, 2022). "In addition, recent research revealed that the increased level of GSDMB contributed to inducing an asthma phenotype characterized by AHR and airway remodeling without lung inflammation." (PMID 36248872, 2022). "This suggests that the predominant genetic effect of the GSDMB polymorphism is on allergy and not asthma per se." (PMID 36201519, 2022).
asthma (continued). "Recently, Panganiban et al43 proved that GSDMB might contribute to asthma through GSDMB‐dependent pyroptosis in airway epithelial cells." (PMID 34590363, 2021). "Multiple GWAS and functional studies relate asthma to ORMDL3 and GSDMB however to our knowledge no studies have been published investigating this variant or linked genes with regards to neutrophils in asthma." (PMID 35386986, 2021). "Similar to GSDMB, ORM1-like 3 in 17q is associated with asthma." (PMID 34858408, 2021). "Gasdermin B (GSDMB) locus on chromosome 17q21 is associated with childhood-onset asthma in ethnically different populations In close proximity to GSDMB, ORMDL3 gene showed a highly reproducible association with childhood onset asthma at GWAS." (PMID 33925009, 2021). "Although the genetic linkage between GSDMB and asthma, its biological function in asthma pathogenesis remains unknown." (PMID 33925009, 2021). "The colocalized SNP is in LD (r2 > 0.85 in the 1000 Genomes CEU reference panel) with other previously reported asthma-associated GWAS SNPs in this region, including some that were reported as eQTLs for ORMDL3 and GSDMB, primarily in resting blood immune cells." (PMID 34629083, 2021). "Importantly, functional validation of GWAS candidate asthma risk genes have uncovered key roles in HRV infection susceptibility (ORMDL3 and CDHR3) and TGFβ signalling (GSDMB, TGFBR1, and SMAD3)." (PMID 32887352, 2020). "Employing this approach, Ober and colleagues reported that only two SNPs in the 17q region were associated with asthma in African American children, and these SNPs were correlated with expression of GSDMB but not ORMDL3 in airway epithelial cells." (PMID 32887352, 2020). "For example, strong evidence is found for site-specific DNAm as an intermediary via which disease variants regulate ORMDL3, GSDMB, and JAZF1 expression by CD4+ T cells in RA, MS, and asthma, and a similar mechanism in relation to ANKRD55 and IL6ST is limited to RA and MS." (PMID 31945409, 2020). "The gene encoding the zona pellucida-binding protein 2 (ZPBP2) has been revealed as a common locus of both childhood and adulthood asthma by several studies, supported by the association of several intronic SNPs as well as variants located within the intergenic region of ZPBP2 and GSDMB." (PMID 30805318, 2019). "This genomic region consists of a number of genes, including ORMDL3, GSDMB, IKZF3, ZPBP2, and GSDMA that are in LD and may either be individually or jointly responsible for the asthma association." (PMID 30541564, 2018). "GSDMA is along with GSDMB and ORMDL3 part of the complex 17q21.1 locus, more research is needed to understand the specific interactions of variants in this region and their role in asthma pathobiology." (PMID 30373671, 2018). "We also found evidence that the association between GSDMB KO and asthma described in our GWAS analysis above is non-additive." (PMID 29691392, 2018). "Similarly, a recent study found that the PTV rs11078928 in GSDMB that offers protection against asthma removes exon 6 from the transcript and eliminates the ability of GSDMB to induce cell death." (PMID 29691392, 2018). "A severe asthma GWAS identified a novel locus, CDHR3, that had not been observed using broader asthma definitions, in addition to the known asthma susceptibility loci GSDMB, IL33, and IL1RL1." (PMID 28774304, 2017). "The GSDML encodes for gasdermin B protein expressed in epithelial barrier function and skin differentiation, influencing the expression of the neighbouring gene ORMDL3 and thus contributing to asthma susceptibility." (PMID 25299150, 2014). "Recently, a GWAS study focusing on childhood asthma has identified a locus on chromosome 17q12-21 (encoding ORMDL3 and GSDMB) as a risk factor for predominantly childhood-onset asthma, but not for atopy, and overall not for adult-onset asthma." (PMID 23936416, 2013).